ADGRE3 (adhesion G protein-coupled receptor E3)
Description:
Orphan receptor that may play a role myeloid-myeloid interactions during immune and inflammatory responses. A ligand for the soluble form of this receptor is present at the surface of monocytes-derived macrophages and activated neutrophils.
Synonyms: EMR3
Tractability: Antibody: its Gene Ontology location is reachable by antibodies, with high confidence; UniProt places it where antibodies can reach, with medium confidence; UniProt predicts a signal peptide or a membrane-spanning region.
Gene: Protein-coding gene on chromosome 19 (14,599,080 to 14,690,027, reverse strand). Ensembl gene ENSG00000131355.
Subcellular location: Cell membrane; Secreted (Isoform 3)
Pathways (Reactome):
Immune System: Neutrophil degranulation
Signal Transduction: Class B/2 (Secretin family receptors)
Gene Ontology:
Molecular function: G protein-coupled receptor activity; calcium ion binding; transmembrane signaling receptor activity
Biological process: G protein-coupled receptor signaling pathway; cell surface receptor signaling pathway
Cellular component: ficolin-1-rich granule membrane; membrane; plasma membrane; secretory granule membrane; extracellular region
Genetic constraint (gnomAD): Loss-of-function variants: 68 observed, 65.79 expected, observed/expected ratio (o/e) 1.03, 90% interval 0.85 to 1.26. The upper end of that interval is the gene's LOEUF score, 1.26, which puts it in group 5 of 6, group 1 being the genes least tolerant of losing a copy. Missense variants: 654 observed, 736.04 expected, observed/expected ratio (o/e) 0.89, 90% interval 0.83 to 0.95. Synonymous variants: 264 observed, 285.68 expected, observed/expected ratio (o/e) 0.92, 90% interval 0.83 to 1.02.
Homologues: Orthologues: chimpanzee ADGRE3 (98% identical), pig ADGRE3 (71% identical), dog ADGRE3 (71% identical). Paralogues in human: ADGRE2 (54% identical), ADGRE1 (37% identical), ADGRE5 (36% identical), ADGRL1 (32% identical), ADGRL2 (31% identical), ADGRL3 (31% identical), ADGRL4 (28% identical), ADGRD1 (23% identical), ADGRB1 (22% identical), ADGRF1 (21% identical), ADGRG4 (21% identical), ADGRG2 (21% identical), and 30 more.
Diseases named in the same sentence as ADGRE3 in open-access papers:
ADGRE3 is named in the same sentence as 15 diseases in open-access papers, as found by Europe PMC text mining. Sharing a sentence is not in itself a finding about the gene and the disease. The quoted sentences say what the papers report.
Sepsis (3 papers, 2022 to 2024). Sepsis is defined as life-threatening organ dysfunction caused by a dysregulated host response to infection. "TDRD9 and ADGRE3 were chosen since they have been previously demonstrated to be part of the SRS1 signature in sepsis." (PMID 36389738, 2022).
lung carcinoma (2 papers, 2022 to 2025). "Furthemore, ADGRE3 and OR51E1 expression was positively correlated with sensitivity to the drugs cisplatin, ribociclib, and pevonedistat, chemotherapeutics commonly used or being investigated in clinical trials for lung cancer." (PMID 40364562, 2025).
tumor (4 papers, 2021 to 2025). "Tumor stage and the ADGRD1, ADGRE3, and LGR4 genes were identified to be independently associated with the prognosis of patients with LUAD." (PMID 40364562, 2025). "In both TCGA‐LUAD, in the GSE30219 and GSE18842 cohorts, the expression of ADRB1, ADGRD1, and ADGRE3 were reduced, whereas the expression of OR51E1 and LGR4 were elevated in tumor samples." (PMID 40364562, 2025).
ADGRE3 also shares sentences with these, for which no sentence is quoted: glioblastoma (4 papers); Alzheimer disease (1); asthma (1); bladder cancer (1); congenital heart defects (1); endometriosis (1); melanoma (1); metastatic melanoma (1); nasal polyp (1); neurodevelopmental disorder (1); polyp (1); rubella (1).